TRBV15 (T cell receptor beta variable 15)
Synonyms: TCRBV15S1; TCRBV24S1A3T
Gene: T-cell receptor variable (V) gene on chromosome 7 (142,592,928 to 142,593,473, forward strand). Ensembl gene ENSG00000276819.
Gene Ontology:
Biological process: cell surface receptor signaling pathway
Cellular component: plasma membrane
Homologues: Orthologues: macaque TRBV15 (90% identical), mouse Trbv17 (60% identical). Paralogues in human: TRBV7-9 (43% identical), TRBV10-3 (40% identical), TRBV5-5 (40% identical), TRBV7-3 (40% identical), TRBV7-7 (40% identical), TRBV11-1 (39% identical), TRBV5-1 (39% identical), TRBV5-6 (39% identical), TRBV7-6 (39% identical), TRBV10-1 (38% identical), TRBV11-2 (38% identical), TRBV11-3 (38% identical), and 39 more.
Diseases named in the same sentence as TRBV15 in open-access papers:
TRBV15 is named in the same sentence as 2 diseases in open-access papers, as found by Europe PMC text mining. Sharing a sentence is not in itself a finding about the gene and the disease.
TRBV15 shares sentences with these, for which no sentence is quoted: COVID-19 (1 paper); infection (1).